CUX2 (cut like homeobox 2)
Description:
Transcription factor involved in the control of neuronal proliferation and differentiation in the brain. Regulates dendrite development and branching, dendritic spine formation, and synaptogenesis in cortical layers II-III. Binds to DNA in a sequence-specific manner.
Synonyms: CUTL2; KIAA0293; CDP2; DEE67; EIEE67
Tractability: PROTAC: ubiquitination databases record sites on it.
Safety:
Unwanted effects reported when the protein is acted on. In parentheses: how it was acted on, where the effect was seen, and who reports it.
liver toxicity (source: ClinPGx)
Gene: Protein-coding gene on chromosome 12 (111,033,853 to 111,350,554, forward strand). Ensembl gene ENSG00000111249.
Subcellular location: Nucleus
Gene Ontology:
Molecular function: sequence-specific DNA binding; sequence-specific double-stranded DNA binding; DNA-binding transcription factor activity, RNA polymerase II-specific; RNA polymerase II transcription regulatory region sequence-specific DNA binding; DNA binding; DNA-binding transcription repressor activity, RNA polymerase II-specific; RNA polymerase II cis-regulatory region sequence-specific DNA binding
Biological process: cognition; negative regulation of transcription by RNA polymerase II; positive regulation of dendrite morphogenesis; positive regulation of dendritic spine morphogenesis; positive regulation of excitatory postsynaptic potential; positive regulation of gene expression; positive regulation of synapse assembly; regulation of transcription by RNA polymerase II; short-term memory; regulation of DNA-templated transcription
Cellular component: extracellular exosome; nucleus; chromatin
Genetic constraint (gnomAD): Loss-of-function variants: 37 observed, 126.93 expected, observed/expected ratio (o/e) 0.29, 90% interval 0.22 to 0.38. The upper end of that interval is the gene's LOEUF score, 0.38, which puts it in group 1 of 6, group 1 being the genes least tolerant of losing a copy. Missense variants: 1,597 observed, 1,851.2 expected, observed/expected ratio (o/e) 0.86, 90% interval 0.83 to 0.9. Synonymous variants: 818 observed, 812.27 expected, observed/expected ratio (o/e) 1.01, 90% interval 0.95 to 1.07.
Gene-disease validity (ClinGen):
ClinGen rates the evidence that CUX2 causes each of these diseases.
genetic developmental and epileptic encephalopathy (autosomal dominant): Moderate. A complex neurodevelopmental disorder characterized by a range of developmental delays and epileptic encephalopathy phenotypes.
Homologues: Orthologues: macaque CUX2 (98% identical), chimpanzee CUX2 (97% identical), dog CUX2 (93% identical), pig CUX2 (92% identical), rabbit CUX2 (86% identical), guinea pig CUX2 (86% identical), rat Cux2 (83% identical), mouse Cux2 (80% identical), tropical clawed frog cux2 (66% identical), zebrafish cux2b (53% identical), Drosophila melanogaster ct (27% identical), Caenorhabditis elegans cone-1 (20% identical). Paralogues in human: CUX1 (44% identical).